KLF2 (KLF transcription factor 2)
Diseases named in the same sentence as KLF2 in open-access papers (continued):
Sharing a sentence is not in itself a finding about the gene and the disease.
breast carcinoma (continued). "KLF2 expression levels were found to be reduced in advanced cancer stages and grades, while positively correlated with the expression of estrogen receptor (ER), progesterone receptor (PR), and tumor size in breast cancer." (PMID 37123417, 2023). "Furthermore, our results showed that KLF2 or KLF15 can be used as a prognostic factor independent on the other KLFs in patients with breast cancer." (PMID 35033064, 2022). "Next, we assessed whether KLF2 or KLF15 overexpression in breast cancer cells can influence breast cancer proliferation and migration by KLF2- or KLF15-transfected MDA-MB-231 cells." (PMID 35033064, 2022). "The expression of KLF2 showed a significant upregulation in Invasive Breast Carcinoma Stroma, Invasive Ductal Breast Carcinoma Epithelia, Ductal Breast Carcinoma in Situ Epitheli, while other 13 dataset displayed an obvious downregulation across different subtypes." (PMID 35033064, 2022). "The expression of KLF2/4/6/8/9/11/15 was significantly down-regulated in breast cancer." (PMID 35033064, 2022). "Knockdown of RUSC1-AS1 via inhibiting cell cycle progression through the KLF2/CDKN1A axis could induce apoptosis in breast cancer cells." (PMID 33330110, 2020). "A subsequent study on mammary carcinoma imputed to Kruppel-like factor 2 (KLF2) the shifting of ATRA signaling from the pro-oncogenic FABP5/PPARβ/δ path to the anti-carcinogenic CRABPII/RAR pathway, inducing the expression of CRABPII and inhibiting the expression of FABP5 and PPARβ/δ." (PMID 32012980, 2020). "KLF2 is a tumor suppressor gene, which inhibits cell growth, migration, and invasion in numerous types of cancer, such as colorectal cancer, breast cancer, and prostate cancer." (PMID 32256525, 2020). "In breast cancer, several lines of evidence have implicated overexpression of EZH2 and repression of tumor suppressors such as KRT5, KRT6, CDH3, RAD51 paralogs, CDKN1C, FOXC1, Wnt/β-catenin signaling (c-Myc, Cyclin D1, Axin2), RKIP and KLF2." (PMID 27835578, 2016). "It was also reported that KLF2 suppresses the expression of FABP5 in MCF-7 mammary carcinoma cells." (PMID 26416422, 2015). "Taken together, the data show that KLF2 appreciably contributes to the development of some human breast cancers and point at this factor and its downstream effectors, RA binding proteins and nuclear receptors, as novel targets for therapy of some human breast cancers." (PMID 26416422, 2015). "Notably, the deposited data show that high mRNA level of KLF2 correlates with markedly better survival rates of breast cancer patients." (PMID 26416422, 2015). "Considering that NF-κB is activated by epidermal growth factor receptors (EGFR), the amplification of the EGFR gene HER2/ERBB2/neu in a significant fraction of human breast cancers may provide a partial explanation for downregulation of KLF2 in breast tumors." (PMID 26416422, 2015). "It has been proposed that KLF2 could have a tumor suppressor activity in the MCF-7 mammary carcinoma cells." (PMID 23634293, 2013). "Taken together, KLF2 may serve as a marker for the clinical diagnosis of breast cancer." (PMID 37123417, 2023). "Therefore, our findings suggest that KLF2 may function as a tumor suppressor in breast cancer, consistent with previous reports." (PMID 37123417, 2023). "In breast cancer cell lines, UM171 was shown to activate the expression of tumor suppressor gene KLF2 and cell cycle inhibitor P21." (PMID 38874684, 2024). "Through analysis of breast cancer datasets from TCGA in BCIP, we determined the difference in KLF2 expression between breast cancer and normal samples." (PMID 37123417, 2023). "Notably, the anticancer drug simvastatin could induce KLF2 expression in both breast cancer." (PMID 37123417, 2023). "Thus, KLF2 may serve as a promising biomarker for breast cancer diagnosis and treatment." (PMID 37123417, 2023).
breast carcinoma (continued). "To further assess the relationship between KLF2 and immune cell infiltration in breast cancer, we conducted an analysis of the TIMER database to explore the correlation between KLF2 and immune cell marker genes in different types of immune cells." (PMID 37123417, 2023). "In breast cancer, eight winning TFs (ZBTB16, KLF2, KLF4, NR2F1, EGR1, FOSB, EPAS1, and GPRASP1) can form a coregulatory network, and three other winning TFs (MYBL2, FOXM1, and TAL1) can form another coregulatory network." (PMID 36101460, 2022). "KLF2 and KLF15 function as tumor suppressors in breast cancer and are potential biomarkers for prognostic prediction in patients with breast cancer." (PMID 35033064, 2022). "Collectively, these results indicate that KLF2 and KLF15 induce cell cycle arrest and cell apoptosis in breast cancer." (PMID 35033064, 2022). "Together, these results indicate that KLF2 and KLF15 function as tumor suppressors in breast cancer." (PMID 35033064, 2022). "The results showed that both KLF2 and KLF15 expression was significantly lower in breast cancer cell lines, especially in the triple-negative breast cancer cell lines CAL51 and MDA-MB-231." (PMID 35033064, 2022). "In the current study, we aimed to investigate the role of KLFs in breast cancer progression and found that the expression of KLF2 and KLF15 can be used as the prognostic predictor in patients with breast cancer." (PMID 35033064, 2022). "Although the prognostic signatures based on KLFs expression have been investigated in several studies, we found that both KLF2 and KLF15 can be used as prognostic predictors independent on other KLFs in patients with breast cancer." (PMID 35033064, 2022). "We next performed in vitro experiments to assess the effect of KLF2 and KLF15 on the biological behaviors in breast cancer cells." (PMID 35033064, 2022). "Taken together, these results suggest that KLF2 and KLF15 can be used as prognostic predictor in patients with breast cancer." (PMID 35033064, 2022). "We next compared the transcription levels of KLFs between breast cancer and normal tissues using GEPIA and found that KLF2/4/6/8/9/11/15 were significantly downregulated in tumor tissues." (PMID 35033064, 2022). "Consistent with previous study, we demonstrated that KLF2 and KLF15 inhibits breast cancer proliferation and migration." (PMID 35033064, 2022). "We next employed GSEA analysis to explore the relevant signaling pathways of KLF2 and KLF15 high expression group and low expression group in patients with breast cancer." (PMID 35033064, 2022). "MDA-MB-231 triple negative mammary carcinoma cells, and an MDA-MB-231 cell line that stably over-expresses KLF2 (inset) were injected into NCr athymic mice and tumor growth was monitored." (PMID 26416422, 2015). "Furthermore, the study observed a significant correlation between KLF2 CNV and infiltration levels of CD4+ T cells and macrophages in breast cancer patients." (PMID 37123417, 2023). "Our RNA-seq data of simvastatin-treated breast cancer cells showed significantly upregulated the mRNA level of KLF2 (data not shown)." (PMID 37123417, 2023). "Furthermore, we demonstrated that KLF2 and KLF15 can function as tumor suppressors in breast cancer." (PMID 35033064, 2022). "Finally, in vitro experimental validation was confirmed KLF2 and KLF15 functioning as tumor suppressors, resulted in the inhibition of cell proliferation and migration in breast cancer." (PMID 35033064, 2022). "In summary, the dysregulation expression of KLF2 and KLF15 in breast cancer tissues might play an important role in BC oncogenesis." (PMID 35033064, 2022). "Our study demonstrated that KLF2 and KLF15 function as tumor suppressors, may serve as prognostic biomarkers in patients with breast cancer." (PMID 35033064, 2022). "Finally, we investigated the effect of KLF2 and KLF15 on biological behavior of breast cancer cells in vitro." (PMID 35033064, 2022).
breast carcinoma (continued). "The molecular events that lead to suppression of KLF2 during breast cancer development are incompletely understood but it is worth noting that it has been reported that KLF2 expression is inhibited by NF-κB." (PMID 26416422, 2015). "Our findings suggest that KLF2 may inhibit tumor angiogenesis and growth in breast cancer by inhibiting the VEGFA-HIF pathway, and thus KLF2 may be an important anti-angiogenesis therapeutic target for breast cancer." (PMID 37123417, 2023). "Unlike MDA-MB-231 cells, MCF-7 mammary carcinoma cells express a high level of KLF2." (PMID 26416422, 2015). "Intra-family comparison showed no matter how much other KLFs expressed, both KLF2 and KLF15 expression levels can distinguish RFS of patients with breast cancer independent other KLFs expression levels." (PMID 35033064, 2022). "We firstly determined the expression levels of KLF2 and KLF15 in different breast cancer cell lines and the normal breast cell line by RT-PCR and western blot." (PMID 35033064, 2022). "Additionally, KLF2 expression decreased from normal-like, luminal, HER2-enriched to basal-like in the different subtypes of breast cancer tissues, and was highly expressed in non-triple negative breast cancer (TNBC) than in TNBC." (PMID 37123417, 2023).
colorectal cancer (16 papers, 2017 to 2024). A primary or metastatic malignant neoplasm that affects the colon or rectum. "Colorectal cancer cell derived exosomes miR-25-3p targeted KLF2 and KLF4 to regulate the expression of VEGFR2, ZO-1, occludin and Claudin5, increase vascular permeability and promote angiogenesis." (PMID 35173549, 2022). "Exosomes from colorectal cancer cells contained miR-25-3p, which regulate vascular permeability and angiogenesis by suppressing the expression of Kruppel-like factor 2 (KLF2) and Kruppel-like factor 4 (KLF4)." (PMID 34239869, 2021). "CCK-8 results revealed that silencing of KLF2 or CDKN2B (P15) partially abolished SNHG1 knockdown induced growth arrest of colorectal cancer cells." (PMID 30266084, 2018). "SNHG1 promotes colorectal cancer cell growth through epigenetic silencing of KLF2 and CDKN2B in the nucleus." (PMID 30266084, 2018). "High expression of SNHG1 in patients with colorectal cancer can interact with EZH2 to regulate histone methylation of Krüppel-like factor 2 (KLF2) and cyclin-dependent kinase inhibitor 2B (CDKN2B) in the nucleus and affect the biological behavior of colorectal cancer cells." (PMID 40226409, 2023). "(e) The relation between KLF2 and SNHG1 expression analyzed in colorectal cancer samples from TCGA cohort (n = 478, r = − 0.24, P < 0.001)." (PMID 30266084, 2018). "Long non-coding RNA HOXA-AS2 represses P21 and KLF2 expression transcription by binding with EZH2, LSD1 in colorectal cancer." (PMID 29221147, 2017). "Exosomal miR-25-3p derived from Colorectal cancer (CRC) cells could be absorbed by endothelial cells to facilitate, angiogenesis and increasing vascular permeability via targeting KLF2 (kruppel like factor 2) and KLF4 (kruppel like factor 4)." (PMID 35255950, 2022). "To investigate whether KLF2 and CDKN2B were involved in the SNHG1 induced promotion of colorectal cancer cell growth, we performed rescue assays." (PMID 30266084, 2018). "Mechanistic investigations revealed that SNHG1 could exhibit different regulatory mechanisms in the nucleus and cytoplasm, and it could promote the development of colorectal cancer by regulating CCND2, KLF2 and CDKN2B expression." (PMID 30266084, 2018). "FOXP4-AS1, expressed highly in colorectal cancer (CRC) tissue, can promote the colorectal cancer cell proliferation, inhibit apoptosis, and downregulate the tumor-suppressor gene expression including P15, P21, P27, and KLF2, which are positively related to tumor size and pathological stages." (PMID 35720005, 2022). "(c) KLF2 expression was analyzed in colorectal cancer samples and normal samples from TCGA cohort." (PMID 30266084, 2018). "Finally, we observed a negative correlation between SNHG1 and KLF2 or CDKN2B expression in colorectal cancer tissues by analyzing RNA sequencing data from TCGA database." (PMID 30266084, 2018).
hepatocellular carcinoma (13 papers, 2015 to 2024). A malignant tumor that arises from hepatocytes. "KLF2 inhibits tumor cell growth and migration in hepatocellular carcinoma (HCC), non-small cell lung cancer (NSCLC), and clear cell renal cell carcinoma (ccRCC)." (PMID 39454432, 2024). "There was KLF2 down regulation in hepatocellular cancer (HCC) tissue that suppressed the cell growth and metastasis by repressing the Hedgehog/Gli1 signaling cascade." (PMID 37807067, 2023). "For example, lncRNA GHET1 indicates poor prognosis and facilitates cell proliferation through silencing KLF2 expression in hepatocellular carcinoma." (PMID 33109776, 2020). "The duplicate: “Huang M-d, Chen W-m, Qi F-z, Xia R, Sun M, Xu T-p, Yin L, Zhang E-b, De W, Shu Y-q Long non-coding RNA ANRIL is upregulated in hepatocellular carcinoma and regulates cell apoptosis by epigenetic silencing of KLF2." (PMID 28950881, 2017). "Evidence were found suggesting that that KLF2, part of the Krüppel-like factor (KLF) family, is involved in the development of preventing hepatocellular carcinoma (HCC)." (PMID 35992798, 2022).
liver fibrosis (13 papers, 2017 to 2025). "Chen and colleagues have demonstrated that the long non-coding RNA known as Airn can mitigate the progression of liver fibrosis by modulating the KLF2-eNOS-sGC signaling pathway." (PMID 39857310, 2025). "The findings further demonstrate that the expression level of KLF2 decreased continuously during the process of liver fibrosis to cirrhosis and then to hepatocarcinogenesis." (PMID 37386390, 2023). "Long noncoding RNAs can interact with EZH2, and maintain LSEC differentiation through KLF2-eNOS-sGC pathway and alleviate CCl4-induced liver fibrosis." (PMID 36828540, 2023). "This is consistent with previous work with statin drugs on liver fibrosis, where KLF2 upregulation was observed after treatment with simvastatin." (PMID 29322934, 2017). "Experiments displayed that in the hepatic fibrosis mice model with POFUT1 knockout in LSECs, POFUT1 deficiency inhibited the KLF2-eNOS-sGC signaling axis, promoting injury-induced LSEC capillarization, while up-regulating the expression of fibrinogen in LSEC through the NOTCH/HES1/STAT3 pathway." (PMID 40761743, 2025). "Similarly, the targeted maintenance of LncRNA Airn function can maintain the differentiation of LSECs through the KLF2-eNOS-sGC pathway, thereby inhibiting the activation of HSCs and preventing liver fibrosis." (PMID 37999580, 2023). "Our model predicts that one of the ways KLF2 may contribute to improvement of liver fibrosis may be by decreasing the activation of TGF-β1 through reduction of the TSP1 and PAI feedback effects." (PMID 29322934, 2017). "Increased KLF6 expression augments enhanced collagen 1 and TGFß1 expression to result in liver fibrosis, and overexpression of KLF2 induces expression of the fatty acid translocator CD36 whereas KLF15 plays an essential role in ER stress-mediated insulin resistance in the liver." (PMID 29296203, 2017). "Kruppel-like factor 2 (KLF2), a transcription factor capable of positively regulating the eNOS-sGC pathway maintains LSECs differentiation, has been demonstrated to facilitate the inactivation of HSCs activation and apoptosis to alleviate liver fibrosis by Simvastatin." (PMID 40761743, 2025). "In conclusion, our study highlights the considerable therapeutic potential of using SIM‐LipoNPs to prevent liver fibrosis progress, underscoring the remarkable properties of SIM‐LipoNPs in activating the KLF2‐NO pathway and anti‐oxidative and anti‐inflammatory response." (PMID 38984945, 2024).
heart failure (12 papers, 2009 to 2026). Inability of the heart to pump blood at an adequate rate to meet tissue metabolic requirements. "Although the small sample size prevents generalization of the inverse association between KLF2 expression and heart failure, it is nevertheless an intriguing observation that requires further investigation." (PMID 35104806, 2022). "In mouse, loss of Klf2 is associated with heart failure and altered cardiac output." (PMID 19924233, 2009). "Leukocytes from human and murine models of heart failure were characterized by markedly decreased expression of Kruppel-like factor 2 (Klf2), a suppressor of myeloid inflammatory activation." (PMID 36009397, 2022). "Leukocytes from human subjects and a rodent model of heart failure were characterized by a marked reduction in expression of Klf2 mRNA." (PMID 34793333, 2022). "CCM complex disruption in the endocardium modulates the MEKK3‐MEK5‐ERK5 axis to upregulate Klf4 and Klf2 expression resulting in mid‐gestation heart failure." (PMID 26612856, 2016). "KLF2 ablation leads to myocardial thinning, high output cardiac failure and death by mouse embryonic day 14.5 (E14.5) in a mixed genetic background." (PMID 23457456, 2013). "This avenue of research may lead to therapeutic strategies for heart failure aimed at promoting KLF2 function in neutrophils, or limiting neutrophil activation, NET formation, or microvascular thrombosis and dysfunction." (PMID 35104806, 2022). "In summary, the interaction between neutrophils, NET formation, and factors such as KLF2 and CRP is crucial in the progression and exacerbation of heart failure." (PMID 39130369, 2024). "In cases of heart failure, NETosis is regulated by inflammatory molecules such as C-reactive protein (CRP), and Krüppel-like factor 2 (KLF2) – a protein that plays a role in controlling inflammation, and angiotensin II." (PMID 39130369, 2024). "In mammals, the regulation of autophagy by KLFs, including KLF2, KLF4 and KLF6, is also involved in vascular aging, heart failure, and cell aging." (PMID 37543362, 2023). "The consistent lack of KLF-2 would lead to cardiac failure after long-term high output responding to a too-low peripheral resistance as recently shown in a model of KLF-2 knockout mice." (PMID 37373238, 2023).